SGK1 (serum/glucocorticoid regulated kinase 1)
Diseases named in the same sentence as SGK1 in open-access papers (continued):
Sharing a sentence is not in itself a finding about the gene and the disease.
gastric cancer (12 papers, 2016 to 2026). A primary or metastatic malignant neoplasm involving the stomach. "In our study, the Th2 and Th17 response was confirmed to be dominant in H. pylori-positive gastric cancer, which is linked to Lnc-SGK1 and SGK1 was overexpression." (PMID 26942879, 2016). "Most research on SGK1has focused on its role in cancer cells, and we sought to investigate its potential upstream non-coding RNA nominated as Lnc-SGK1, and their expression and diagnostic value in T cells in human gastric cancer (GC)." (PMID 26942879, 2016). "Overexpression of ER-α36 promoted the proliferation, migration, and invasion of gastric cancer cells, while SGK1 knockdown abolished these oncogenic effects." (PMID 42121888, 2026). "Lnc-SGK1 induces expression of glucocorticoid-inducible kinase 1 (SGK1) to induce Th2 and Th17 differentiation and inhibit Th1 differentiation in Hp-infected gastric cancer." (PMID 37153158, 2023). "In human gastric cancer, serum Lnc-SGK1 expression in T cells in combination with H. pylori (Hp) infection and/or a high-salt diet (HSD) was associated with poor prognosis of GC patients." (PMID 33542904, 2020). "For example, studies have reported an association between signal transduction of serum and glucocorticoid-induced protein kinase 1 (SGK1) with occurrence and progression of malignancies, including gastric cancer." (PMID 33193896, 2020). "ER-α36, SGK1, and p-Erk1/2 were co-upregulated in gastric cancer tissues and cells." (PMID 42121888, 2026). "In addition, lnc-SGK1 (Serine/threonine-protein kinase-SGK1) promotes Th2 and Th17 differentiation by SGK1/JunB signaling in gastric cancer." (PMID 33194608, 2020). "In gastric cancer patients, serum Lnc-SGK1 expression in combination with H. pylori infection was significantly associated with poor prognosis and could be an ideal diagnostic index in human GC." (PMID 33542904, 2020).
Hyperglycemia (12 papers, 2012 to 2025). An increased concentration of glucose in the blood. "Nerveless, the molecular mechanisms underlying SGK1 dysregulation under hyperglycemia remain to be elucidated." (PMID 37079269, 2023). "There is also evidence that SGK1 is implicated in glucose metabolism in the kidney during the progression of hyperglycemia-induced organ damage." (PMID 37079269, 2023). "Equally important, how SGK1 regulates ROS production and pyroptosis under hyperglycemia challenge warrants further investigations." (PMID 37079269, 2023). "There is also evidence that SGK1 is engaged in glucose metabolism in the intestine and kidney during the progression of hyperglycemia-induced secondary organ damage." (PMID 37079269, 2023). "Although ubiquitously expressed, transcription of SGK1 is highly regulated by various cellular events, such as hyperglycemia, ischemia, and cancer, and stimulated by glucocorticoids, mineralocorticoids, insulin, and TGFβ." (PMID 36457711, 2022). "In previous in vitro studies, by inducing cellular transgenic activation of SGK1, we demonstrated as this kinase protected kidney cells from apoptosis, and endothelial cells from oxidative stress and hyperglycemia." (PMID 32547392, 2020). "SGK1-downstream osteoinductive signaling involving NF-κB activation participates in the vascular pro-calcific effects of hyperglycemia." (PMID 33003561, 2020). "Moreover, hyperglycemia is known to induce NKCC1 expression via the activation of the serum-glucocorticoid kinase 1 (SGK1)–NKCC1 pathway." (PMID 32645929, 2020). "However, the expression of serum-glucocorticoid kinase 1 (SGK1) is known to be upregulated in hyperglycemia, and increased SGK1 expression is known to augment the expression of NKCC1." (PMID 32645929, 2020). "SGK1 mediates, at least partly, the osteoinductive effects of hyperglycemia in VSMCs." (PMID 33003561, 2020). "The changes in expression of these proteins may be due to significant improvement in hyperglycemia since high glucose has been shown to increase the expression of SGK1 and ENaC in distal renal tubular cells in vitro." (PMID 28086951, 2017). "Notably, SGK1 expression is characterized by remarkably high transcriptional volatility and is regulated by a variety of physiological and pathological stimuli, including hyperglycemia, cell shrinkage, ischemia, glucocorticoids, and mineralocorticoids." (PMID 41030847, 2025). "This implies that SGK1 and Nedd4L are involved in the development of hyperglycemia-induced cardiomyopathy, future studies are warranted to validate whether targeting SGK1 and Nedd4L could provide a solution for the clinical treatment of diabetic cardiomyopathy or not." (PMID 35429991, 2022). "Thus, SGK1 is required for the development of vascular calcification during hyperglycemia." (PMID 33003561, 2020). "Together, these findings suggest that suppression of miR29c in energy homeostasis related tissues, as a response to hyperglycemia and hyperlipidemia, may play a part in goose fatty liver by modulating energy metabolism via its target genes, Insig1, Sgk1 and Col3a1." (PMID 30400792, 2018). "Furthermore, SGK1 interference may impact glucose absorption and hyperglycemia." (PMID 33003561, 2020).
cardiac hypertrophy (11 papers, 2014 to 2025). "In insulin-resistant female diabetic mice, increased myocardial expression of SGK1 and ENaC caused myocardial fibrosis and eccentric LV hypertrophy, while empagliflozin reduced SGK1 and ENaC levels, as well as related pro-fibrotic signals, leading to an improved diastolic relaxation." (PMID 38935171, 2025). "Activation of SGK1 has been associated with cardiac hypertrophy, in which increased phosphorylated SGK1 and phosphorylated FoxO1, a downstream target of SGK1, were observed following cardiomyocyte treatment with phenylephrine (PE), a cardiac hypertrophic stimulant." (PMID 36457711, 2022). "SGK1 was activated and induced ventricular remodeling, including fibrosis and ventricular hypertrophy, after aorta fasciculation in rats." (PMID 37691190, 2023). "Increasingly, studies have confirmed that SGK1 and epithelial sodium channels have a contributing effect on fibrosis and harmful myocardial hypertrophy." (PMID 37691190, 2023). "In the present study, we reported Ext.R attenuated pressure‐induced cardiac hypertrophy via inhibiting SGK1 phosphorylation for the first time." (PMID 34761560, 2022). "Taken together, these data suggest INSR, IGF1R, AKT3 and SGK1 are novel target genes contributing to mir15a/mir16‐1 inhibition‐mediated cardiac hypertrophy." (PMID 33377640, 2020). "The study elucidated the effect of miR-133a on HG-cardiac hypertrophy by downregulating SGK1 and IGF1R mRNAs." (PMID 24528626, 2014). "It is proved that extract of Rhodiola species attenuates cardiac hypertrophy via targeting SGK1." (PMID 34761560, 2022). "Moreover, a panel of nine flavonoids with SGK1 inhibitory activities was proposed, which can be used as valuable leads for the search and design of new therapeutics for cardiac hypertrophy as well as other SGK1‐driven diseases." (PMID 34761560, 2022). "Through transcriptomics‐based KEGG pathway analysis, we speculated that SGK1 was a key factor mediating the regulatory function of Ext.R in cardiac hypertrophy." (PMID 34761560, 2022). "During hypertrophic stress, increased C/EBPβ downregulates the mir15a/mir16‐1 cluster, resulting in up‐regulation of multiple target proteins (INSR, IGF1R, AKT3, SGK1) in cardiomyocytes, causing increased activation of insulin/IGF1 signaling, ultimately causing cardiac hypertrophy and dysfunction." (PMID 33377640, 2020). "Notably, these changes were effectively inhibited in AngII-infused mice treated with EMD638683, suggesting that SGK1 was involved in AngII-induced cardiac hypertrophy in mice." (PMID 30524295, 2018). "In addition, SGK1 itself may induce cardiac hypertrophy and promote arrhythmia." (PMID 36059970, 2022). "Using this strategy, we identified HBT as a novel inhibitor of SGK1, and we showed that HBT was capable of blocking the progress of cardiac hypertrophy both in vitro and in vivo." (PMID 34761560, 2022). "Thermal shift assay, KINOMEscan in vitro assay combined with molecular docking were used to reveal the binding domain of HBT and SGK1, and the pharmacological mechanism of HBT against cardiac hypertrophy was further studied." (PMID 34761560, 2022). "It was found that SGK1 inhibitor EMD638683 significantly prevented renal function and cardiac hypertrophy, as well as renal and cardiac fibrosis, in AngII-infused mice." (PMID 30524295, 2018). "Cardiac hypertrophy in mice is characterized by chronic activation of growth-promoting signaling pathways downstream of the insulin receptor, with increased activation of AKT and SGK1 contributing to a hypertrophic response in various conditions." (PMID 32990683, 2020). "Finally, the investigators transfected the HG-exposed cardiomyocytes with custom-synthesized miR-133a mimics and observed the attenuation of hypertrophy along with downregulation of SGK1 and IGF1R mRNAs, the targets of miR-133a in cardiac hypertrophy." (PMID 24528626, 2014).
hepatocellular carcinoma (11 papers, 2016 to 2025). A malignant tumor that arises from hepatocytes. "Factors including Sgk1 have also been considered as the cause of decreased sensitivity of cytotoxic drug therapy by activating the GC-GR pathway in hepatocellular carcinoma and colon adenocarcinoma." (PMID 32106831, 2020). "Particularly, resveratrol inhibited SGK1 activity in hepatocellular carcinoma cells and also in a cell-free kinase assay." (PMID 34679726, 2021). "In the present report, we have demonstrated that SI113-dependent SGK1 inhibition induces a generalized down-regulation of miRNA expression in hepatocellular carcinoma cells." (PMID 28358001, 2017). "SGK1 specific inhibitors have been tested in several neoplastic models, including colon and hepatocellular carcinoma." (PMID 26908461, 2016). "SGK1 may be upregulated in some cancers, but its expression could also be down-regulated in prostate, ovarian, and hepatocellular carcinoma." (PMID 40613901, 2025). "BARD1 mutation is reported in 1.1% of hepatocellular adenomas, SGK1 mutation is observed in numerous tumor types, and TERT is also one of the most commonly mutated genes in hepatocellular carcinoma, with mutations predominantly in the reporter region that regulates gene expression, as in this case." (PMID 38903310, 2024). "A recent article revealed a positive correlation between SGK1 expression and T-cell exhaustion features in hepatocellular carcinoma and suggested the possibility that the mTORC2-AKT-FOXO1 and mTORC2-SGK1 pathways are important regulatory axes for T-cell exhaustion." (PMID 37582972, 2023). "Also, decreased SGK-1 mRNA expression accompanies a fluvastatin-induced reduction in resistance to chemotherapeutics and prevention of migration of breast and hepatocellular carcinoma cells." (PMID 35048019, 2021). "Moreover, genome-wide analysis of gene expression in human hepatocellular carcinoma (HCC) cells demonstrates that SGK1 and its cognate kinase AKT1 are equally over-expressed when compared with normal human hepatocytes, suggesting that both kinases might have roles in hepatocellular dysregulation." (PMID 26908461, 2016).
Parkinson disease (11 papers, 2011 to 2024). A progressive degenerative disorder of the central nervous system characterized by loss of dopamine producing neurons in the substantia nigra and the presence of Lewy bodies in the substantia nigra and locus coeruleus. "The glucocorticoid-responsive gene SGK1 has been implicated in Alzheimer’s disease and Parkinson’s disease." (PMID 35458399, 2022). "Sgk1, a glucocorticoid-responsive gene that has been implicated in Alzheimer’s disease and Parkinson’s disease, was elevated in HIV Tg rats vs. WT rats that escalated their oxycodone self-administration under LgA conditions." (PMID 35458399, 2022). "In Parkinson disease, SGK1 was found overexpressed and SGK1 knockdown suppressed pro‐inflammatory activities of glia through inhibiting the NLRP3‐ and NFκB‐mediated inflammatory pathways." (PMID 39555740, 2024). "In a mouse model of MPTP-induced Parkinson, acupuncture was found to up-regulate the expression of SGK1 thereby decreasing the aggregation of α-syn." (PMID 39737082, 2024). "In this study, we show that inhibition of SGK1 in glia treats Parkinson disease (PD) via suppressing glial inflammation and potentiating glial neurotrophic functions." (PMID 33646633, 2021). "Although the cause of aggregation of α-syn is unknown, it was found that decreased expression of SGK1 in MPTP-induced Parkinson's mouse model and SH-SY5Y cells may lead to dopaminergic cell death through increased expression and aggregation of α-syn." (PMID 39737082, 2024). "In the face of these urgent problems, many scholars found that SGK1 plays a significant role in the occurrence and development of Parkinson's disease, stroke, etc., suggesting that the regulation of SGK1 may be a therapeutic target or a potential drug." (PMID 39737082, 2024). "In addition to oligodendrocytes, it has been shown that Sgk1 or SGK1 is expressed in neurons in several diseases such as Parkinson's disease, Huntington's disease, amyotrophic lateral sclerosis (ALS), and ischemia." (PMID 25705664, 2015). "In addition to oligodendrocytes, it has been shown that Sgk1 or SGK1 is expressed in the neurons in several diseases such as Parkinson's disease, Huntington's disease, amyotrophic lateral sclerosis (ALS), and ischemia." (PMID 21655274, 2011). "Therefore, this article reviews the role of SGK1 in Alzheimer's disease, Parkinson's disease, epilepsy, stroke and other neurological diseases in recent years, and puts forward some insights on the role of SGK1 in neurological diseases and its relationship with disease activities." (PMID 39737082, 2024). "Furthermore, SGK1 inhibition potentiated glial activity to scavenge glutamate toxicity and prevented glial cell senescence and mitochondrial damage, which have recently been reported as critical pathologic features of and therapeutic targets in Parkinson disease (PD) and Alzheimer disease (AD)." (PMID 33646633, 2021).
Anxiety (10 papers, 2016 to 2025). Intense feelings of nervousness, tension, or panic often arise in response to interpersonal stresses. "Together, these studies reinforce the idea that SGK1 plays a critical role in the development of anxiety-associated disorders and anxiety-induced hyperalgesia." (PMID 34093127, 2021). "This study suggests that brain SGK1 is potentially involved in pain and anxiety behaviors associated with arthritis by modulating ASIC1a." (PMID 34093127, 2021). "Previous studies have demonstrated that Sgk1 upregulation in mice is associated with neurodegeneration, impairments in learning and memory, and anxiety- and depressive-like behaviors, which may contribute to the development of these deficits in NEXOX mice." (PMID 40606839, 2025). "Neither sex showed a difference in center time during the open filed task, which may suggest that anxiety-like behaviors are unaltered by DA SGK1 KO." (PMID 32901079, 2020). "Interestingly, previous research has demonstrated that SGK1 may upregulate glucocorticoid receptor phosphorylation, counteracting the cortisol-induced reduction in hippocampal neurogenesis from anxiety and depressive-like behaviors." (PMID 35884632, 2022).
type 2 diabetes (10 papers, 2008 to 2025). "In the same samples, INS expression was reduced and SGK1 gene induction, which has been associated with insulin release and type 2 diabetes, was inhibited." (PMID 37250333, 2023). "Interestingly, SGK1 polymorphisms (located in both Intron 6 and Exon 8) have recently been found to be associated with type 2 diabetes in Romanian and German cohorts." (PMID 19461886, 2009). "Additionally, SGK1 upregulates ion channels, including ENaC, and is likewise a potent inducer of the SGLT1, a novel cardiac glucose transporter in type 2 diabetes." (PMID 28086951, 2017).
Alzheimer disease (9 papers, 2019 to 2026). A progressive, neurodegenerative disease characterized by loss of function and death of nerve cells in several areas of the brain leading to loss of cognitive function such as memory and language. "The availability of iPSC-derived cortical neurons from AD patients and the discovery of SGK1 and HDAC6 as key targets based on pathogenic mechanisms would stimulate further research and drug discovery in Alzheimer’s disease." (PMID 40921794, 2026). "Construction of tissue-specific delivery systems: Abnormal activation of SGK1 in the bones, kidneys, and central nervous system is closely related to the pathological processes of osteoporosis, diabetic nephropathy, and Alzheimer’s disease." (PMID 40427579, 2025). "SGK1 expression is widely detected in the brain, and it is increased in pathologic conditions such as Rett syndrome, Alzheimer disease, multiple sclerosis, amyotrophic lateral sclerosis, and neuropathic pain." (PMID 33646633, 2021). "Inhibition of AKT and phosphorylated glycogen synthase kinase 3β (GSK3β) increases apoptosis, but PI3K/AKT-mediated up-regulation of SGK1 reverses this trend and prevents apoptosis, which has a positive effect on cerebral ischemia, Alzheimer's disease, and other neurological diseases." (PMID 39737082, 2024).
lung carcinoma (9 papers, 2011 to 2025). "SGK1 has recently been linked with resistance to DNA damage-induced apoptosis in ERCC excision repair 1 (ERCC1)-defective lung cancer cells, suggesting an indirect involvement with specific types of DNA damage." (PMID 33266470, 2020). "Next, we explored the therapeutic potential of targeting the demethylation SGK1 in the immunosuppressive function of MDSCs in a mouse subcutaneous lung cancer model." (PMID 40917754, 2025). "For example, the top SNP rs9493858 is located on the SGK1 gene, which is suggested to be affected in lung cancer in several studies." (PMID 32957998, 2020). "Several of those miRNAs that are known to be deregulated in lung cancer are also predicted to target SGK1." (PMID 33266470, 2020). "To further investigate the effect of TET2-mediated SGK1 demethylation in vivo, we constructed a mouse subcutaneous lung cancer model and randomly divided the mice into two groups: siNC-MDSC (MDSCs transfected with siNC) and siTET2-MDSCs (MDSCs transfected with siTET2-MDSCs)." (PMID 40917754, 2025). "In NSCLC, the chromosomal region including NDRG1 is consistently amplified and the gene over-expressed SGK1 can promote stem-like properties of lung cancer cells by preventing c-Myc degradation through ubiquitination operated by the S-phase kinase-associated protein 2 (Skp2)." (PMID 33266470, 2020). "In nonsmall-cell lung cancer, C-containing genotypes of MIAT rs1061451 were found to be protective factors in NSCLC, and myocardial infarction associated transcript (MIAT), which may act as a ceRNA via miR-133a-5p, modulated the SGK1 expression level." (PMID 33542904, 2020).